PDHB (pyruvate dehydrogenase E1 subunit beta)
Description:
Together with PDHA1 forms the heterotetrameric E1 subunit of the pyruvate dehydrogenase (PDH) complex. The PDH complex catalyzes the overall conversion of pyruvate to acetyl-CoA and CO(2), and thereby links cytoplasmic glycolysis and the mitochondrial tricarboxylic acid (TCA) cycle (Probable). It contains multiple copies of three enzymatic components: pyruvate dehydrogenase (E1), dihydrolipoamide acetyltransferase (E2) and dihydrolipoamide dehydrogenase (E3) (Probable). The E1 subunit catalyzes both the thiamine pyrophosphate (TPP)-dependent decarboxylation of pyruvate and the reductive acetylation of a lipoyl group covalently linked to the lipoyl-bearing domains of E2.
Synonyms: PDHE1-B; PHE1B; PDHE1B; E1beta; PDHBD
Tractability: Small molecule: a structure with a bound ligand is known; it has a binding pocket of medium quality. PROTAC: ubiquitination databases record sites on it; its protein half-life has been measured.
Target class: Enzyme; Oxidoreductase
Gene: Protein-coding gene on chromosome 3 (58,427,630 to 58,434,012, reverse strand). Ensembl gene ENSG00000168291.
Subcellular location: Mitochondrion matrix
Subcellular location (Human Protein Atlas): Mitochondria; Cell Junctions; Nucleoplasm
Pathways (Reactome):
Metabolism: PDH complex synthesizes acetyl-CoA from PYR; Regulation of pyruvate dehydrogenase (PDH) complex
Metabolism of proteins: Mitochondrial protein degradation
Signal Transduction: Signaling by Retinoic Acid
Gene Ontology:
Molecular function: protein binding; pyruvate dehydrogenase (acetyl-transferring) activity
Biological process: pyruvate decarboxylation to acetyl-CoA; tricarboxylic acid cycle
Cellular component: mitochondrion; nucleus; pyruvate dehydrogenase complex; mitochondrial matrix
Genetic constraint (gnomAD): Loss-of-function variants: 11 observed, 31.05 expected, observed/expected ratio (o/e) 0.35, 90% interval 0.22 to 0.59. The upper end of that interval is the gene's LOEUF score, 0.59, which puts it in group 2 of 6, group 1 being the genes least tolerant of losing a copy. Missense variants: 255 observed, 372.21 expected, observed/expected ratio (o/e) 0.69, 90% interval 0.62 to 0.76. Synonymous variants: 124 observed, 124.44 expected, observed/expected ratio (o/e) 1, 90% interval 0.86 to 1.16.
Gene-disease validity (ClinGen):
ClinGen rates the evidence that PDHB causes each of these diseases.
Leigh syndrome (autosomal recessive): Moderate. A progressive neurological disease defined by specific neuropathological features associating brainstem and basal ganglia lesions.
Homologues: Orthologues: chimpanzee PDHB (100% identical), rabbit PDHB (97% identical), dog PDHB (96% identical), guinea pig PDHB (96% identical), rat Pdhb (94% identical), mouse Pdhb (94% identical), pig PDHB (92% identical), macaque PDHB (89% identical), tropical clawed frog pdhb (84% identical), zebrafish pdhb (84% identical), Drosophila melanogaster Pdhb (66% identical), Caenorhabditis elegans pdhb-1 (64% identical). Paralogues in human: BCKDHB (35% identical), TKTL2 (25% identical), TKTL1 (25% identical), TKT (24% identical).
Diseases named in the same sentence as PDHB in open-access papers:
PDHB is named in the same sentence as 76 diseases in open-access papers, as found by Europe PMC text mining. Sharing a sentence is not in itself a finding about the gene and the disease. The quoted sentences say what the papers report.
breast carcinoma (11 papers, 2018 to 2025). "We identified the expression of cuproptosis-related mRNA across five distinct breast cancer subtypes, revealing that only two genes, PDHB and PRNP, exhibited significant differential expression within this cohort." (PMID 38408075, 2024). "Consistent with the data from R language, starBase showed that expression levels of CDKN2A, SLC31A1, ATP7B, and PDHB were markedly up-regulated in breast cancer with respect to normal samples." (PMID 37884650, 2023). "PDHB has been reported to be associated with high PRA: PRB in mammary gland of transgenic mice in breast cancer, which indicates breast cancer malignant progression." (PMID 36699089, 2022). "Further, we determined a significant overlap of the pathways characterizing PRA transgenics and those in breast cancer subtypes Luminal A and Luminal B and identified novel putative biomarkers, such as PDHB and LAMB3." (PMID 29940887, 2018). "FDX1 (P < 1E‐12), LIAS (P = 2.22E‐16), LIPT1 (P < 1E‐12), DLD (P < 5.46E‐09), DLAT (P = 3.14E‐02), PDHA1 (P = 1.15E‐07), MTF1 (P = 1.07E‐09), and GLS (P = 2.48E‐05) were downregulated in breast cancer, while PDHB (P = 5.04E‐07) and CDKN2A (P = 1.62E‐12) were upregulated." (PMID 39432636, 2024). "We analyzed the expression pattern of CRGs in breast cancer tissues and non-tumor tissues based on TCGA and GTEx dataset, illustrating that CDKN2A, DLD, DLAT, MTF1 and PDHB expression were significantly elevated in breast cancer compared with their normal tissues." (PMID 36518756, 2022). "Therefore, FDX1, LIPT1, and PDHB have favorable prognostic values before breast cancer recurrence." (PMID 39432636, 2024). "PDHB and CDKN2A expression were significantly higher in breast cancer tissues compared with control." (PMID 37353799, 2023).
colorectal cancer (10 papers, 2021 to 2023). A primary or metastatic malignant neoplasm that affects the colon or rectum. "Overexpression of PDHB can reverse miR-146b-5p carcinogenic effects on the development, invasion, and glycolysis of colorectal cancer (CRC) cells." (PMID 36891324, 2023). "For example, miR-146b-5p controls colorectal cancer cell proliferation, invasion, and metabolism targeting PDHB." (PMID 36882799, 2023). "Previous studies have found that PDHB is known to be closely related to colorectal cancer, renal cancer, and other malignant diseases." (PMID 36249422, 2022). "In addition, it has been shown that inhibition of PDHB promotes colorectal cancer growth and metastasis." (PMID 37533853, 2023). "Another related study showed that pyruvate dehydrogenase E1β subunit (PDHB) may be involved in the occurrence and development of colorectal cancer (CRC) under the regulation of LncRNA maternally expressed gene 3 (MEG3)." (PMID 36335291, 2022). "Similarly, other researchers found that PDHB was involved in circadian clock and could regulates metabolic phenotype in colorectal cancer, which influenced tumor progression and drug response." (PMID 37350959, 2023). "We also found that PDHB and DLD were differentially expressed in colorectal cancer, while FDX1 was distinctly expressed in lung adenocarcinoma." (PMID 36506302, 2022). "It has been reported that PDHB exerts an anticancer effect by counteracting oncogenic noncoding RNAs, such as miR-370, miR-363-3p, and miR-146b-5p, in melanoma, glioma, and colorectal cancer, respectively." (PMID 36386799, 2022).
gastric cancer (5 papers, 2022 to 2024). A primary or metastatic malignant neoplasm involving the stomach. "Aberrant expression of PDHA1 and PDHB, which were involved in glycolytic regulation, was also closely associated with poor prognosis in gastric cancer patients." (PMID 35790864, 2022). "PDHB is aberrantly expressed in gastric cancer and is associated with a better prognosis." (PMID 37533853, 2023). "Overexpression of PDHB switches cell metabolism from glycolysis to the Krebs cycle in gastric cancer and epithelial ovarian carcinoma." (PMID 36386799, 2022). "PDHB expression is lower in gastric cancer patients than in normal individuals, with lower PDHB expression being associated with poor patient prognosis." (PMID 36092880, 2022). "We conducted molecular experiments to validate our findings, and the results of Western blot analysis revealed notable disparities in the expression levels of FDX1, LIAS, DLAT, DLST, GCSH, PDHB and PDHA1 in gastric cancer cells between the CSRS‐Low (AGS) and CSRS‐High (HGC‐27) subtypes." (PMID 38898987, 2024).
lung carcinoma (5 papers, 2018 to 2023). "The PDHB gene is a key component involved in gluconeogenesis, and previous studies have demonstrated that high expression levels in lung cancer patients are associated with reduced overall survival, which is consistent with our findings." (PMID 37450406, 2023). "In M. pneumoniae, PDHA and PDHB bind to HeLa and A549 cells (a human lung carcinoma cell line) in ELISA assays with HeLa cell-coated or A549 cell-coated plates." (PMID 30532176, 2018). "In a word, our study showed that FDX1, a key enzyme for cuproptosis, affected the prognosis of lung cancer patients by influencing the expression of GLS, PDHA1, PDHB, DLAT, and MTF1." (PMID 36620594, 2022). "FDX1 affects the prognosis of lung cancer by altering the expression of cuproptosis-related signature (GLS, PDHA1, PDHB, MTF1, and DLAT), which more strongly confirms that the prognosis of lung cancer patients is closely related to the occurrence of cuproptosis." (PMID 36620594, 2022). "In addition to CDKN2A, genes, including DLD, LIPT1, GLS, PDHB, and PDHA1, also have significant CNVs, indicating the heterogeneity of lung cancer tissue." (PMID 36712848, 2022).
ovarian carcinoma (5 papers, 2017 to 2022). A malignant neoplasm originating from the surface ovarian epithelium. "Zhao found that PDHB is associated with ovarian cancer growth and metastasis, and miR-203 can target the 3’-UTR of PDHB to promote glycolysis." (PMID 36341437, 2022). "We explored the potential of YY1, FDX1, DLD, DLAT, and PDHB to serve as non-invasive diagnostic markers of ovarian cancer." (PMID 36484005, 2022). "The results of the cDNA expression profile analysis showed that four factors (i.e. FDX1, DLD, DLAT, PDHB) were highly expressed in the tumor tissues of ovarian cancer patients." (PMID 36484005, 2022). "Our study revealed that the expression of four core factors of the lipoic acid pathway (i.e., FDX1, DLD, DLAT, and PDHB) was distinct between ovarian cancer patients and normal tissues and that it was significantly correlated with a poor prognosis inovarian cancer patients." (PMID 36484005, 2022). "Meanwhile, overexpression of PDHB could abolish the promoting effect of miR-203 on ovarian cancer cell growth." (PMID 36341437, 2022). "We used an exosome database for screening and found that the levels of FDX1, DLD, DLAT, PDHB, and YY1 in peripheral blood exosomes from ovarian cancer patients were significantly higher than those in the normal controls." (PMID 36484005, 2022). "Kaplan-Meier plotter analysis showed that except for LIAS, PDHB, and ATP7B, the factors related to PDHB were significantly negatively correlated with the survival cycle of ovarian cancer patients." (PMID 36484005, 2022). "In addition, the expression levels of YY1 in the tissue samples from ovarian cancer patients were significantly positively correlated with the expression levels of FDX1, DLD, DLAT, PDHB, and other genes." (PMID 36484005, 2022). "Among CNV increasing genes, only DLD in ovarian cancer samples was higher than that in normal ovarian tissues, while the expression levels of DBT, PDHB, ATP7B, etc. with CNV deletion were not consistent with CNV changes." (PMID 36307842, 2022).
glioma (4 papers, 2017 to 2023). A benign or malignant brain and spinal cord tumor that arises from glial cells (astrocytes, oligodendrocytes, ependymal cells). "On the other hand, IDH1MUT glioma showed higher expression levels of PDHA (in glioblastoma), PDHB (in LGG) and PDHX as compared to IDH1WTglioma." (PMID 28467784, 2017). "We performed receiver operating characteristic curve (ROC) analyses to assess whether various CRG levels aided glioma detection; the areas under the curves (AUCs) were >0.9 for CDKN2A, FDX1, DLD, and PDHB." (PMID 36579333, 2022). "For OS outcomes of glioma patients, a 9-gene signature was selected to construct the prognostic score using their regression coefficients: Riskscore = (0.8949)*FDX1 + (0.4902)*DLD + (0.0778)*DLAT + (-0.9324)*LIAS + (0.1132)*GLS + (0.903)*LIPT1 + (-0.1847)*MTF1 + (-0.2352)*PDHA1 + (-0.2045)*PDHB." (PMID 36915038, 2023). "In addition to the levels of GLS, MTF1, and PDHB, those of the other seven CRGs significantly affected the OS, DSS, and PFI of glioma patients; cuproptosis may play a major role in disease progression." (PMID 36579333, 2022).
melanoma (4 papers, 2021 to 2023). A malignant, usually aggressive tumor composed of atypical, neoplastic melanocytes. "CRGs with low and moderate CNV, such as PDHA1, DLAT, GLS, and LIAS, were overexpressed in CRC comparison to those in normal melanoma samples, whereas CRGs with high CNV, such as PDHB, were significantly increased in melanoma samples, implying that CNV may regulate CRG mRNA expression." (PMID 36824136, 2023). "However, the expression of PDHA1, PDHB, and GLS was significantly higher in melanoma than in normal tissues." (PMID 36824136, 2023).
sarcopenia (4 papers, 2023 to 2025). Progressive decline in muscle mass due to aging which results in decreased functional capacity of muscles. "In addition, several features of d‐gal‐induced sarcopenia, such as loss of grip strength, decreased gastrocnemius muscle mass and accumulation of lactic acid and calcium, were partially ameliorated by PDHB overexpression." (PMID 36564038, 2023). "According to the results of ROC analysis, PDHA1, DLAT, PDHB, and NDUFC1 were selected as the potential promising diagnostic biomarkers of sarcopenia." (PMID 37007946, 2023). "PDHA1 and PDHB were downregulated in sarcopenia patients, which indicated the dysfunction of mitochondrial respiration in sarcopenia patients." (PMID 37007946, 2023). "The four hub genes (PDHA1, DLAT, PDHB, and NDUFC1) were included to construct a diagnostic model for sarcopenia." (PMID 37007946, 2023). "Our findings indicate the cuproptosis-related genes, PDHA1, DLAT, PDHB, and NDUFC1 are the diagnostic biomarker for sarcopenia, which provide evidence concerning the role of cuproptosis in sarcopenia." (PMID 37007946, 2023). "Thus, the PDHB signalling contributes to skeletal muscle differentiation and can be targeted as a potential therapy in sarcopenia." (PMID 36564038, 2023). "The comprehensive results show that PDHB plays a sarcoprotective role by suppressing the FoxP1–Arih2 axis and may serve as a therapeutic target in sarcopenia." (PMID 36564038, 2023). "We further conducted an in vivo study to explore whether overexpression of PDHB promotes myogenic differentiation and improves sarcopenia." (PMID 36564038, 2023). "Additionally, overexpressing PDHB in skeletal muscle alleviated D-galactose-induced sarcopenia in mice." (PMID 38159255, 2023). "Moreover, PDHB overexpression in skeletal muscle alleviated d‐gal‐induced sarcopenia in mice." (PMID 36564038, 2023). "A total of four overlapping genes were extracted as the hub genes involved in sarcopenia and cuproptosis, which were PDHA1, DLAT, PDHB and NDUFC1." (PMID 37007946, 2023). "Intersection of DEGs, WGCNA and CRGs yielded four core genes (PDHA1, DLAT, PDHB, and NDUFC1) as potential biomarkers for the prediction of sarcopenia." (PMID 37007946, 2023). "A total of four possible hub genes of sarcopenia were screened, namely, PDHA1, DLAT, PDHB, and NDUFC1." (PMID 37007946, 2023). "The present study inferred the significance of mitochondrial dysfunction in the progression of sarcopenia, and the four cuproptosis-related genes, PDHA1, DLAT, PDHB, and NDUFC1, may serve as the potential targets for further therapeutic intervention." (PMID 37007946, 2023).
Sepsis (4 papers, 2024 to 2025). Sepsis is defined as life-threatening organ dysfunction caused by a dysregulated host response to infection. "Downregulation of PDHB is strongly associated with development of sepsis." (PMID 40182687, 2025). "A bioinformatic analysis of the relationship between the pathogenesis of sepsis and cuproptosis-related genes identified LIAS and PDHB as potential diagnostic biomarkers for cuproptosis-associated sepsis." (PMID 40182687, 2025). "Finally, the 6 DECuGs (ANKRD9, DLD, LIPT1, MTF1, PDHB, UBE2D4) as diagnostic biomarkers for sepsis were identified by the intersection of the two machine learning algorithms." (PMID 38495196, 2024). "Next, six key DECuGs (ANKRD9, DLD, LIPT1, MTF1, PDHB, UBE2D4) were identified as diagnostic biomarkers based on the two machine learning algorithms, suggesting their potential functional importance in the pathogenesis of sepsis." (PMID 38495196, 2024). "Notably, only PDHB demonstrated remarkable prognostic utility in sepsis." (PMID 39671358, 2024). "For immune cells, monocytes, T cells, B cells, and NK cells were related to DLD, LIPT1, MTF1, PDHB and UBE2D4 in the sepsis group." (PMID 38495196, 2024). "Since PDH activity is often inhibited in patients with sepsis, modification of PDHB and PDHA1 seems to significantly influence the development of sepsis." (PMID 39539553, 2024). "PDHB, a crucial regulatory subunit of PDH, is yet to unveil its precise role in sepsis/SIC." (PMID 39671358, 2024).
clear cell renal cell carcinoma (2 papers, 2022 to 2023). "Pyruvate dehydrogenase E1 subunit beta (PDHB) is one of the cuproptosis genesand is a nuclear-encoded pyruvate dehydrogenase, which catalyzes the conversion of pyruvate to acetyl coenzyme A. However, the mechanism of PDHB in clear cell renal cell carcinoma (ccRCC) remains unclear." (PMID 37641032, 2023). "So far, the effect of PDHB expression on renal clear cell carcinoma remains unclear." (PMID 37641032, 2023). "The results demonstrated that ATP7B, DLAT, and LIAS were upregulated in the 786-O cell line, which represented human renal clear cell adenocarcinoma cell, compared to the HK-2 cell line; while DBT and PDHB were found to be downregulated in 786-O cells." (PMID 36092880, 2022). "The expression of PDHB in metastatic ccRCC was lower than that in non-metastatic renal clear cell carcinoma (p < 0.05)." (PMID 37641032, 2023).
developmental delay (2 papers, 2022 to 2023). "Recessive PDHB mutations cause pyruvate dehydrogenase complex (PDC) deficiency, which mainly affects the nervous system, such as developmental delays, seizures, and peripheral neuropathy." (PMID 36979852, 2023).
glioblastoma (2 papers, 2017 to 2022). The most malignant astrocytic tumor (WHO grade IV). "Most copper induced cell death genes were downregulated in various cancers, such as FDX1 in cholangiocarcinoma (CHOL); LIAS and LIPT1 in bladder cancer (BLCA); PDHB in glioblastoma (GBM) and kidney chromophobe cancer (KICH)." (PMID 36581992, 2022).
Mycoplasma pneumonia (2 papers, 2021 to 2022). "The moonlighting function for PdhB, as a fibronectin-binding protein facilitating host colonization and disease pathogenesis, was shown for the pathogen Mycoplasma pneumonia." (PMID 34070083, 2021).
osteoarthritis (2 papers, 2023 to 2024). A noninflammatory degenerative joint disease occurring chiefly in older persons, characterized by degeneration of the articular cartilage, hypertrophy of bone at the margins and changes in the synovial membrane. "Results of this study involving a risk model showed that the copper cell death gene PDHB might be a risk factor for osteoarthritis." (PMID 36982438, 2023). "Additionally, five genes related to cuproptosis (FDX1, LIPT1, PDHA1, PDHB, and CDKN2A) are considered candidate biomarkers or therapeutic targets for osteoarthritis synovitis." (PMID 39360273, 2024).
pyruvate dehydrogenase deficiency (2 papers, 2021 to 2025). A rare neurometabolic disorder characterized by a wide range of clinical signs with metabolic and neurological components of varying severity. "These included initiation of a ketogenic diet to patients with pyruvate dehydrogenase deficiency (mutations in PDHA1, PDHB, DLD), AGC1 deficiency (mutations in SLC25A12), and GLUT1 deficiency (mutations in SLC2A1)." (PMID 33726816, 2021).
acute myocardial infarction (1 paper, 2024). Necrosis of the myocardium, as a result of interruption of the blood supply to the area. "In contrast, patients with acute myocardial infarction exhibit decreased levels of LIAS, PDHB, LIPT1, DLAT, and GLS, along with increased MTF1 levels." (PMID 39360273, 2024).